MC1R (melanocortin 1 receptor)
Diseases named in the same sentence as MC1R in open-access papers (continued):
Sharing a sentence is not in itself a finding about the gene and the disease.
melanoma (continued). "Thus, it is possible a defective activation of this pathway leads to malignant transformation and, if this is the case, ATM penetrance could be modulated by UV exposure and/or the co-occurrence of other inherited melanoma predisposing factors, such as phototype and MC1R variants." (PMID 34262154, 2021). "MC1R variants have been shown to increase the penetrance of CDKN2A mutations (observed risk over time for a mutation carrier), doubling the risk of melanoma development." (PMID 34356109, 2021). "Nanoparticles engineered to target the melanocortin-1 receptor expressed on melanoma (B16 melanoma) were loaded with the alpha particle emitter, Actinium-225." (PMID 33503958, 2021). "TRH can bind to the MC1R expressed in B16 melanoma cell lines, where it stimulates the production of c-AMP." (PMID 34068618, 2021). "Melanocortin 1 receptor (MC1R)-targeted radiopeptide [212Pb]VMT01 was employed to deliver α-radiation to melanoma tumors in mice." (PMID 34359580, 2021). "Another explanation could be the patient’s phenotype (e.g., skin type, red hair) and genotype (e.g., MC1R polymorphisms status), sunlight incidence during the year, sun-exposure behavior and the Mediterranean diet which has also been reported as a favorable modifying factor of melanoma incidence." (PMID 33113930, 2020). "The melanocortin receptor 1 (MC1R) is also a highly attractive target as it has been found to be highly expressed in the majority of melanomas." (PMID 32733853, 2020). "And over-expression of Mc1r would enhance melanoma cell migration, whereas the opposite was true when knocked down the Mc1r using small inhibitory RNAs." (PMID 32117457, 2020). "We present a useful model system for studying the development of melanoma in the context of defective MC1R." (PMID 32605315, 2020). "The MC1R/cAMP/MITF pathway is implicated in growth, differentiation and survival of melanocytes, as well as in malignant melanoma." (PMID 32605315, 2020). "MC1R is one of the key regulators in the melanogenesis process of melanocytes, implicating a strong role of melanogenesis pathway in melanoma tumorigenesis." (PMID 32169117, 2020). "The method was successfully applied to identify: four SNPs associated with the risk of hemostasis disorders and three SNPs in gene of melanocortin-1 receptor (MC1R), associated with melanoma and non-melanoma skin cancer risk." (PMID 33050422, 2020). "Cases of melanoma were described across all MC1R genotyping groups (wild‐type, heterozygous, compound heterozygous/homozygous)." (PMID 31111470, 2020). "Biocompatible ultrasmall fluorescent core–shell silica nanoparticles (C′ dots, diameter ∼6.0 nm) have been engineered to target the melanocortin-1 receptor expressed on melanoma through α melanocyte-stimulating hormone peptides attached to the C′ dot surface." (PMID 32013538, 2020). "In the MITF+ group, two patients had amelanotic/hypomelanotic melanomas; both patients carried one red-hair-color (RHC) MC1R variant (R169W, R142H)." (PMID 32054529, 2020). "Currently, CDKN2A, CDK4, and MC1R have been the most investigated genes involved in melanoma pathogenesis." (PMID 33748184, 2020). "While MC1-R was originally proven in melanocyte-derived melanoma cells, there is now also evidence that it is expressed in many types of cells, including immune cells." (PMID 32722640, 2020). "The studies on MC1R mainly focused on melanoma, and the results indicated that patients had significantly longer OS in melanoma tumors with lower expression of MC1R, which was opposite with our expectation." (PMID 32382578, 2020). "Together, these results indicate that MTII elicits PTEN upregulation via MC1R, thereby suppressing melanoma progression through downregulating COX-2/PGE2 signaling." (PMID 31968661, 2020). "It is known that ROS stimulates alpha-melanocyte stimulating hormone production in keratinocytes and binds to the melanocortin 1 receptor on melanoma cells leading to melanogenesis." (PMID 32423183, 2020).
melanoma (continued). "In in vitro MC1R affinity studies on B16-F1 melanoma cells, 43 presented with a high affinity of 2.1 nM (IC50 value, no reference compound tested for comparison)." (PMID 32751666, 2020). "Melanoma is strongly linked to fair skin and red hair, the phenotype of the gene MC1R (melanocortin 1 receptor) polymorphisms." (PMID 32210791, 2020). "The results highlight a central role for MC1R palmitoylation in pigmentation and protection against melanoma." (PMID 32714859, 2020). "In an in vivo B16-F1 melanoma mouse model, the tumor uptake of [99mTc]Tc-43 was in contrast demonstrated to be driven by both receptor types, the MC1R and αvβ3 integrin, which was verified by blocking experiments using the corresponding monospecific peptides." (PMID 32751666, 2020). "Since the M21 cell line was not commercially available at the time of the study, the SK-MEL-1 cell line was chosen as a human melanoma xenograft model based on high MC1R mRNA and DNA copy numbers reported in CCLE." (PMID 31537869, 2019). "As such, inhibiting MC1R depalmitoylation should enhance signaling from this GPCR and prevent the increased melanoma risk associated with MC1R RHC variants." (PMID 30787281, 2019). "MC1R-targeted imaging of melanoma has been extensively studied using mouse melanoma models, most notably, the B16-F10 mouse melanoma cell line which has an exceptionally high receptor density at an average of 22,000 copies of per cell." (PMID 31537869, 2019). "We recently developed α-melanocyte-stimulating hormone (αMSH) derivatives, [68Ga]Ga-CCZ01048 and [18F]CCZ01064, that target the melanocortin 1 receptor (MC1R) for mouse melanoma imaging." (PMID 31537869, 2019). "Significantly, we reveal that MC1R de-palmitoylation is catalyzed by APT2 and consequently ML349, an APT2 inhibitor, rescues defects in MC1R RHC variant signaling and offers a potential avenue to an effective melanoma prevention strategy." (PMID 30787281, 2019). "The SK-MEL-1 cell line with ~972 copies of MC1R/cell was successfully used as a human melanoma model for tracer evaluation." (PMID 31537869, 2019). "Other studies reported that BRCA-associated protein 1 (BAP1) and protection-of-telomeres-1 (POT1) mutations, as well as multiple MC1R variants are also associated with MPM and familial melanomas." (PMID 31382929, 2019). "The melanocortin 1 receptor (MC1-R) is one of the most targeted melanoma antigens and belongs to the melanocortin family of G protein-coupled receptors, which consists of five receptor subtypes, MC1-R to MC5-R." (PMID 30901323, 2019). "To confirm our binding and activation results on the MC1-receptor in melanocytes, we subjected alpha-MSH-responsive mouse melanoma cells for 72 h to various concentrations of MC1R-agonist peptides." (PMID 31817532, 2019). "Co-injection of 20 pmol of natGa-CCZ01048 resulted in a 57% reduction in tumor uptake, indicating the low MC1R expression in human melanoma led to receptor saturation even with only low pmol of injected MC1R-targeting peptides." (PMID 31537869, 2019). "This suggests that molar activity plays an important role on tumor uptake of human SK-MEL-1 melanoma xenograft which has a relatively low MC1R expression level." (PMID 31537869, 2019). "The melanocortin 1 receptor (MC1R) that is overexpressed in most murine and human melanoma metastases is an attractive molecular target for imaging and radiotherapy of melanomas." (PMID 31380457, 2019). "Melanocortin receptor 1 (MC1R) is overexpressed in most melanomas, making it a promising molecular target for diagnosis and peptide receptor radionuclide therapy (PRRT)." (PMID 31163066, 2019). "The difficulty in using established human melanoma cell lines as preclinical tumor models lies in their much lower MC1R density." (PMID 31537869, 2019).
melanoma (continued). "Radionuclide-labeled 1,4,7,10-tetraazacyclododecane-1,4,7,10-tetraacetic acid (DOTA)-chelate has been conjugated to many peptides and provides better specific activity, MC1-R affinity, and stability for melanoma imaging of MC1-R." (PMID 30901323, 2019). "Much work has also been done on targeting melanoma, either through melanin or melanocortin-1 receptor (MC1-R)." (PMID 31259173, 2019). "Our results therefore show that ZDHHC13-activated MC1R palmitoylation plays a critical role in melanoma prevention in vivo." (PMID 30787281, 2019). "For assessment of MC1-R affinity and accumulation in tumor cells in vitro, B16-F1 melanoma and/or 4T1 breast cancer cells were incubated with 111In-labeled 3-arm and 4-arm DOTA-α-MSH with and without α-MSH as a substrate." (PMID 30901323, 2019). "In particular, the melanocortin-1 receptor (MC1R) is highly expressed in 83% of malignant melanoma cell lines, and has low expression in normal tissues making it an attractive target for radionuclide therapy and imaging." (PMID 31659557, 2019). "In vitro efficacy on mouse melanoma cells showed similar potency as for the synthetic MC1R agonist alpha-melanocyte stimulating hormone (NDP-alpha-MSH)." (PMID 31817532, 2019). "MC1-R is an attractive receptor for molecular-targeted imaging and radionuclide therapy of melanoma." (PMID 30901323, 2019). "In this study, the 4-arm DOTA construct was newly applied for conjugation to α-MSH to evaluate specific activity, radiolabeling efficiency, MC1-R affinity, stability, and tumor accumulation in melanoma imaging." (PMID 30901323, 2019). "This challenge was illustrated by using the same radioligand [18F]CCZ01064 to image mouse B16-F10 melanoma (22, 000 MC1R/cell), compared to the human SK-MEL-1 melanoma xenograft (<1, 000 MC1R/cell) at the same time point." (PMID 31537869, 2019). "Increasing MC1R palmitoylation in vivo would potentially diminish melanoma incidence, especially for redheads in whom MC1R signaling is compromised." (PMID 30787281, 2019). "Due to a lower MC1R expression level, a higher molar activity of the radiotracers is required for preclinical imaging using human melanoma models." (PMID 31537869, 2019). "Recently it was reported that MC1R upregulation or activation of cAMP increase cell proliferation in melanoma cells." (PMID 29397551, 2018). "While during alpha-MSH induced melanocyte differentiation CREB is activated through PKA downstream of the MC1R, we find that in melanoma cells CREB constitutively binds to the MITF promoter and contributes to the basal expression of MITF." (PMID 28380427, 2017). "It binds to the melanocortin 1 receptor (MC1R) which is over expressed in mice and human melanoma metastases." (PMID 28767081, 2017). "Further studies have shown a much more complex picture of MC1R effects in the melanocyte: in addition to the UV-protective effect of melanin, MC1R can influence melanoma beyond pigmentation, through the positive effect of cAMP on repair of UV-induced damage." (PMID 29081790, 2017). "A candidate SNP-based analysis of previous BCC/SCC variants showed significant associations between mKCs and only one SNP (rs1805007) at MC1R, known to be associated with BCC, SCC and melanoma was significant." (PMID 28081215, 2017). "Melanogenesis and melanoma progression are interconnected by activation of wingless (WNT), melanocortin 1 receptor (MC1R, Gene ID: 4157), and melanogenesis-associated transcription factor (MITF, Gene ID: 4286) signaling." (PMID 28265786, 2017). "In vitro, this peptide showed rapid internalization by cultured B16-F1 melanoma cells despite an ~10-fold reduced MC1R affinity compared to DOTA-NAP-amide." (PMID 28491052, 2017). "Nevertheless, MC1R is known to be expressed at the surface of human melanocytes, and overexpressed at the surface of murine and human melanoma cells, while MC2R-MC5R has higher expression levels in the brain and the nervous system." (PMID 28714883, 2017).
melanoma (continued). "This work dealt with the analysis of the αMSH/MC1R interaction for its ability to influence proliferation in healthy melanocytes and in melanoma cells, an aspect that has already been investigated in the past in preliminary and sporadic studies." (PMID 29020973, 2017). "In contrast, the MC1R (chromosome 16) and HERC2/OCA2 (chromosome 15) loci, both of which affect pigmentation, lose their significance, implying that they influence melanoma risk through their effects on pigmentation phenotypes." (PMID 28973033, 2017). "MSH is the natural ligand of the melanocortin-1 receptor (MCR1), and octapeptide derivatives of α-MSH containing DOTA were shown to bind specifically to MC1R highly expressed on melanocytes and most malignant melanoma cells." (PMID 29146972, 2017). "Because of its central regulatory role for a host of melanocyte physiological responses, the MC1R signaling pathway is emerging as an ever-increasingly important pharmacologic target in preventing or treating melanoma." (PMID 27303435, 2016). "MC1R protein expression is typically low, with an estimated 700 protein units expressed per melanocyte and somewhat higher numbers on melanoma cells." (PMID 27303435, 2016). "Individuals with defective MC1R signaling are prone to melanoma and other UV induced skin cancers not only because their skin is under-melanized but also because they have a blunted melanocytic DNA repair response." (PMID 27303435, 2016). "The melanocortin 1 receptor (MC1R) is a melanocytic Gs protein coupled receptor that regulates skin pigmentation, UV responses, and melanoma risk." (PMID 27303435, 2016). "A role for MC1R as a growth receptor for melanoma is in agreement with transcriptome analysis of a human melanoma cell line in which MC1R was inhibited by transient transfection of an ASIP cDNA." (PMID 27028866, 2016). "MC1R variants can modify the penetrance of CDKN2A mutations, as carriers of mutations in both genes are at increased risk of developing malignant melanoma compared to individuals carrying a mutation in only one gene." (PMID 26938746, 2016). "The findings that melanocytes with LOF MC1R have reduced DNA repair and antioxidant capacities provide an explanation for the vulnerability of these melanocytes to malignant transformation to melanoma." (PMID 27582758, 2016). "The MC1R gene is a highly polymorphic genetic locus and inherited defects in MC1R function are common among fair-skinned, UV-sensitive and melanoma-prone persons." (PMID 27303435, 2016). "We typed 32 pigmentary SNP markers and sequenced MC1R in 246 healthy individuals and 116 individuals attending periodic control for malignant melanoma development, 50 of which were diagnosed with FAMMM." (PMID 26938746, 2016). "MC1R, was shown to be over-expressed on the surface of melanoma cells that derive form melanocyte cells." (PMID 27980570, 2016). "We conclude that α-MSH and ET-1 and their cognate receptors MC1R and ENDBR reduce the risk for melanoma by maintaining genomic stability of melanocytes via modulating the DNA damage response to solar UVR." (PMID 27582758, 2016). "Normal human and mouse melanocytes and melanoma cells express MC1R, a G-protein coupled receptor that regulates the biogenesis and maintenance of melanosomes, the specialized lysosomal compartments within which melanin pigments are synthesized." (PMID 27028866, 2016). "To clarify this issue, we employed the B16F10 mouse melanoma cell line endogenously expressing MC1R and investigated the contribution of PKA and EPAC to α-MSH-induced CRE activation." (PMID 27612207, 2016). "Future studies of variation in MC1R related to anatomical melanoma presentation are necessary to validate our findings." (PMID 25790105, 2015). "To identify miR-514a regulated targets we conducted a miR-514a-mRNA ‘pull-down’ experiment, which revealed hundreds of genes, including: CTNNB1, CDK2, MC1R, and NF1, previously associated with melanoma." (PMID 25980496, 2015).
melanoma (continued). "It has previously been shown that MC1R variants increased the risk of melanoma in CDKN2A mutation carriers, however in Italian CDKN2A mutations carriers, who have few MC1R variants, other factors influence the risk of developing CM." (PMID 25803691, 2015). "We confirmed the occurrence of Iso1 and Iso2 MC1R-TUBB chimeric mRNA species in a panel of 8 human melanoma cell lines and a human epidermal melanocytic cell line." (PMID 26657157, 2015). "To more thoroughly address whether MC1R variants are associated with tumor characteristics, we present results from individuals diagnosed with a first incident primary tumor in a large population-based case-control study of melanoma: the Genes, Environment and Melanoma (GEM) Study." (PMID 25790105, 2015). "Together these epidemiological and biochemical findings indicate more general protective role of MC1R in both neurodegeneration and melanoma." (PMID 26504519, 2015). "In this study, we found that KSHV induces proteomic and morphological changes in melanocytes and melanoma-derived cell lines, accompanied by deregulation of the endogenous anti-inflammatory responses anchored by the MC1-R/α-MSH signaling axis." (PMID 24701351, 2014). "UV exposure can trigger PTEN interaction with wild-type melanocortin-1 receptor variants, which protects PTEN from WWP2-mediated degradation, leading to AKT inactivation in melanoma." (PMID 24571667, 2014). "The contribution of MC1R to prediction of melanoma was similar to that obtained from measuring self-reported nevi, which is considered a strong and discriminative risk factor." (PMID 24134749, 2013). "Already reported in the early seventies, one of the largely explored targets is the melanocortin-1 receptor (MC1-R), which is also overexpressed in numerous melanoma cases." (PMID 23634303, 2013). "Few high penetrance genes are known in Malignant Melanoma (MM), however, the involvement of low-penetrance genes such as MC1R, OCA2, ASIP, SLC45A2 and TYR has been observed." (PMID 23537197, 2013). "The most prevalent low penetrance locus is the melanocortin 1 receptor gene (MC1R), whose variants have been associated both with melanoma as well as with related traits." (PMID 23393597, 2013). "In contrast, a more recent study reported that another ligand of Mc1r, agouti signal protein stimulated migratory activity of melanoma cells." (PMID 22363655, 2012). "Melanocortin-1-receptor (MC1R, MIM#155555) is one of the major genes that determine skin pigmentation and it has been reported to be associated with risk of melanoma, possibly through the determination of the tanning response of skin to UV radiation." (PMID 22862891, 2012). "Quantitative RTPCR showed that all three specific siRNAs reduced the level of Mc1r transcript, and transwell migration assay showed that each of the siRNAs led to reduction in melanoma migration." (PMID 22363655, 2012). "From the siRNAs tested in vitro, we selected WT1-Mc1r which was the highly effective in down-regulating Mc1r expression and melanoma migration." (PMID 22363655, 2012). "Aside from the in vitro assays for its effect on migration, we also performed in vivo assay and showed that Mc1r can potentially regulate metastatic behavior of melanoma cells." (PMID 22363655, 2012). "Transwell migration assays showed that down-regulating Hyal1, Tspan10, and Mc1r resulted in clearly reduced migration of the melanoma cells." (PMID 22363655, 2012). "Second, α-MSH, another well-established ligand of Mc1r inhibits migration and metastasis of melanoma cells." (PMID 22363655, 2012). "One well-established function of Mc1r in melanocytes and melanoma is to mediate the melanogenic signal." (PMID 22363655, 2012). "First, agouti signal protein, a well-established ligand of Mc1r has been shown to stimulate migration of melanoma cells to a significant level." (PMID 22363655, 2012). "Collectively, these data indicate that Mc1r is somehow involved in mediating migratory signaling in melanoma." (PMID 22363655, 2012).